APOL4 (apolipoprotein L4)
Description:
May play a role in lipid exchange and transport throughout the body. May participate in reverse cholesterol transport from peripheral cells to the liver (By similarity).
Synonyms: ApoL-IV; APOLIV
Tractability: Antibody: UniProt places it where antibodies can reach, with high confidence; UniProt predicts a signal peptide or a membrane-spanning region; its Gene Ontology location is reachable by antibodies, with medium confidence. PROTAC: ubiquitination databases record sites on it.
Gene: Protein-coding gene on chromosome 22 (36,189,124 to 36,204,840, reverse strand). Ensembl gene ENSG00000100336.
Subcellular location: Secreted
Subcellular location (Human Protein Atlas): Vesicles; Predicted to be secreted
Gene Ontology:
Molecular function: lipid binding
Biological process: lipid metabolic process; lipid transport; lipoprotein metabolic process
Cellular component: extracellular region; membrane
Genetic constraint (gnomAD): Loss-of-function variants: 13 observed, 10.01 expected, observed/expected ratio (o/e) 1.3, 90% interval 0.84 to 1.86. The upper end of that interval is the gene's LOEUF score, 1.86, which puts it in group 6 of 6, group 1 being the genes least tolerant of losing a copy. Missense variants: 386 observed, 398.94 expected, observed/expected ratio (o/e) 0.97, 90% interval 0.89 to 1.05. Synonymous variants: 154 observed, 152.19 expected, observed/expected ratio (o/e) 1.01, 90% interval 0.89 to 1.16.
Homologues: Orthologues: macaque APOL4 (71% identical), rat Apol3l1 (38% identical), rat LOC120093819 (37% identical), mouse Apol11a (31% identical), mouse Apol9b (30% identical), mouse Apol9a (29% identical), mouse Apol10b (28% identical), rat Apol9a (28% identical), mouse Apol11b (27% identical), mouse Apol10a (26% identical), zebrafish apol (22% identical), Caenorhabditis elegans F07F6.8 (11% identical), and 1 more. Paralogues in human: APOL3 (56% identical), APOL1 (41% identical), APOL2 (39% identical), APOL6 (24% identical), APOL5 (22% identical), APOLD1 (14% identical).
Diseases named in the same sentence as APOL4 in open-access papers:
APOL4 is named in the same sentence as 25 diseases in open-access papers, as found by Europe PMC text mining. Sharing a sentence is not in itself a finding about the gene and the disease. The quoted sentences say what the papers report.
schizophrenia (3 papers, 2020 to 2024). A major psychotic disorder characterized by abnormalities in the perception or expression of reality. "The expression of APOL1, APOL2 and APOL4 is increased in the brains of schizophrenic patients, and sequence polymorphism in the APOL2-APOL4 intergenic region is associated with a risk for schizophrenia." (PMID 39768205, 2024). "The function of APOL4 and APOL5 is unknown, apart from the lack of apoptotic activity for APOL4 and the genetic association of APOL4 with schizophrenia." (PMID 32530132, 2021). "BNC2 is another gene thought to play a role in human skin color determination, whereas the gene APOL4 is significantly up-regulated in people diagnosed with schizophrenia." (PMID 32853200, 2020).
breast carcinoma (2 papers, 2022). "APOL4 has been found to be a prognostic marker for breast cancer." (PMID 36233633, 2022). "It has been reported that APOL4 may be a prognostic marker for breast cancer." (PMID 36233633, 2022). "APOL3, APOL4, NR1H3, OSBPL1A, MAP2K6, and ZDHHC8 were protective genes for breast cancer prognosis." (PMID 35919504, 2022).
glioma (2 papers, 2022 to 2024). A benign or malignant brain and spinal cord tumor that arises from glial cells (astrocytes, oligodendrocytes, ependymal cells). "The KEGG pathway analysis illustrated that APOL4 was associated with antigen processing and presentation, DNA replication, cytokine–cytokine receptor interaction in glioma, revealing the potential functions of APOL4 in gliomas." (PMID 36233633, 2022). "The analysis of the clinical survival data also confirmed that patients with gliomas with high APOL4 expression had significantly shorter survival times than those with low expression." (PMID 36233633, 2022). "The data from TCGA demonstrated that the high expression of APOL4 was related to a poorer OS of gliomas (LGG + GBM) (p < 0.0001) and LGG (p = 2.9 × 10−7)." (PMID 36233633, 2022). "A survival analysis showed a shorter overall survival (OS) in glioma patients with APOL4 overexpression, and a Cox regression analysis showed that APOL4 was an independent prognostic factor for the OS of glioma patients." (PMID 36233633, 2022). "Here, we aimed to explore the underlying biological functions and prognostic predictive value of Apolipoprotein L4 (APOL4) in glioma." (PMID 36233633, 2022). "In the current study, we found that APOL4 mRNA expression was elevated in gliomas and closely correlated with the tumor grade, with the highest expression in GBM and higher WHO grade 3 than WHO grade 2." (PMID 36233633, 2022). "The overexpression of APOL4 was also correlated with the poorer disease free survival (DFS) of gliomas (GLL + GBM) (p = 1 × 10−15) and LGG (p = 6.3 × 10−6)." (PMID 36233633, 2022). "In conclusion, we found that APOL4 is aberrantly expressed in LGG and GBM than normal tissues, and high APOL4 expression predicts a poor outcome of glioma patients." (PMID 36233633, 2022). "In this study, we downloaded APOL4-related genetic and clinical information from The Cancer Genome Atlas (TCGA), Gene Expression Omnibus (GEO), and Chinese Glioma Genome Atlas (CGGA)." (PMID 36233633, 2022). "The clinical significance of APOL4 in a glioma outcome was explored by the Cox regression analysis and Kaplan–Meier survival analysis." (PMID 36233633, 2022). "APOL4 was also related to the regulation of trans-synaptic signaling, synaptic vesicle cycle, and the glutamate receptor-signaling pathway in gliomas." (PMID 36233633, 2022). "In terms of clinical implications, APOL4 is considered as a prognostic biomarker for gliomas, and anti-APOL4 therapies could prevent glioma progression." (PMID 39768205, 2024). "Glioma patients with a higher expression of APOL4 may be more sensitive to immune checkpoint inhibitors (ICI)." (PMID 36233633, 2022). "Herein, we revealed that the expression of APOL4 may predict the response of glioma patients to ICI therapy." (PMID 36233633, 2022). "GO and KEGG analyses were used to analyze the potential functions of APOL4 in gliomas." (PMID 36233633, 2022). "Additionally, by analyzing the data in the CGGA database, we revealed that the high expression of APOL4 predicted a poorer prognosis in all WHO grade primary gliomas." (PMID 36233633, 2022). "Additionally, APOL4 was related to nicotine addiction, taste transduction, and glutamatergic synapse in gliomas." (PMID 36233633, 2022). "Additionally, we found that the expression of several immune checkpoints was higher in the APOL4-high group than that in the APOL4-low group of gliomas." (PMID 36233633, 2022). "Moreover, the Cox regression analysis confirmed that APOL4 was an independent prognostic biomarker for gliomas." (PMID 36233633, 2022). "Moreover, APOL4 levels correlate with the tumor progression of gliomas." (PMID 39768205, 2024). "Moreover, we found that glioma patients who had a high expression of APOL4 had high TIDE scores, which indicated that they may be more sensitive to ICI therapy." (PMID 36233633, 2022). "Glioma patients with a high expression of APOL4 may be more sensitive to ICI." (PMID 36233633, 2022).
glioma (continued). "APOL4 may regulate the process of gliomas by interplaying or regulating immune checkpoints." (PMID 36233633, 2022). "To evaluate the expression of APOL4 in glioma and normal brain tissues, we further applied the GEPIA website, and the results showed that APOL4 mRNA was elevated in both LGG and GBM compared with normal brain tissues." (PMID 36233633, 2022). "To further discover the potential function of APOL4 in gliomas, we established the PPI network of APOL4 in the STRING and GeneMANIA webtools." (PMID 36233633, 2022). "We further evaluated whether there was a correlation between APOL4 expression and the sensitivity of ICI therapy in glioma patients." (PMID 36233633, 2022). "Moreover, APOL4 expression was related to the WHO grades, the expression of APOL4 in WHO 3 gliomas was higher than that in WHO grade 2 but lower than that in WHO grade 4 gliomas (p < 0.0001)." (PMID 36233633, 2022). "APOL4 expression was positively correlated with immune infiltration (including DC cells, neutrophils, CD8+ T cells, B cells, macrophages, CD4+ T cells, etc.)and microenvironmental parameters (including immune, stromal, and ESTIMATE scores) in gliomas." (PMID 36233633, 2022). "This work also revealed that APOL4 may be a novel biomarker for the prognosis and ICI treatment of gliomas." (PMID 36233633, 2022). "APOL4 expression was increased in glioma specimens compared to normal tissues and correlated dramatically with the WHO grade." (PMID 36233633, 2022). "However, it is not clear exactly how APOL4 mediates the development of gliomas." (PMID 36233633, 2022). "However, no information is available on the role of APOL4 in glioma." (PMID 36233633, 2022). "However, whether these is a relationship between APOL4 and glioma has not been studied." (PMID 36233633, 2022).
colon cancer (1 paper, 2023). "Moreover, we transfected RKO colon cancer cells with APOL1-KO, APOL2-KO, APOL3-KO, APOL4-KO and APOL6-KO." (PMID 36923931, 2023).
epilepsy (1 paper, 2026). A brain disorder characterized by episodes of abnormally increased neuronal discharge resulting in transient episodes of sensory or motor neurological dysfunction, or psychic dysfunction. "Four genes (APOL4, KMT2C, SON, VDR) overlapped a clinical epilepsy panel, supporting the capacity of WGS to recover clinically relevant loci." (PMID 42192833, 2026).
melanoma (1 paper, 2022). A malignant, usually aggressive tumor composed of atypical, neoplastic melanocytes. "In addition to the TIDE prediction, we used subclass mapping to compare the two APOL4 expression subtypes with another published dataset (containing 47 melanoma patients who responded to immunotherapy)." (PMID 36233633, 2022).
osteoarthritis (1 paper, 2022). A noninflammatory degenerative joint disease occurring chiefly in older persons, characterized by degeneration of the articular cartilage, hypertrophy of bone at the margins and changes in the synovial membrane. "HLA-DRB1, CD74 and APOL4 were also found previously to be induced by IFN-γ in osteoarthritis chondrocytes." (PMID 35326396, 2022).
tumor (5 papers, 2022 to 2023). "In conclusion, these findings suggest that APOL4 is associated with the tumor grade and immune infiltrates; APOL4 may be a new and potential biomarker for therapeutic and prognostic evaluations that may further suggest the therapeutic efficacy of immunotherapy." (PMID 36233633, 2022). "The tumor-associated significance of the other seven genes (HIST2H2AA4, UQCRHL, AC008269.1, RAB6D, APOL4, HIST1H2AI, ANKAR, SGMS1) remains unclear." (PMID 35480120, 2022). "Early tumor stage, radical resection, low APOL3 expression, high APOL4 and APOL6 expressions, vascular invasion and HBV infection indicated higher survival rates in the TCGA cohort." (PMID 38017264, 2023). "Nomograms were constructed for tumor stage, radical resection, HBV infection, vascular invasion, APOL3 and APOL4 expression for RFS." (PMID 38017264, 2023).
infection (1 paper, 2025). The state of being infected such as from the introduction of a foreign agent such as serum, vaccine, antigenic substance or organism. "We also detected enhanced transcription of the apolipoproteins APOL1, APOL3, and APOL4, which also act as immune regulators in response to infection." (PMID 41416938, 2025).
APOL4 also shares sentences with these, for which no sentence is quoted: asthma (1 paper); autoimmune thyroid disease (1); cancer (1); diabetes (1); herpes simplex infection (1); inflammatory bowel disease (1); leishmaniasis (1); neuroblastoma (1); nicotine addiction (1); Obesity (1); pertussis (1); staphylococcus aureus infection (1); systemic lupus erythematosus (1); toxoplasmosis (1); tuberculosis (1); type 1 diabetes mellitus (1).